MSH6 (mutS homolog 6)
Diseases named in the same sentence as MSH6 in open-access papers (continued):
Sharing a sentence is not in itself a finding about the gene and the disease.
breast carcinoma (100 papers, 1999 to 2026). "Genetic testing revealed a pathogenic CHEK2 nonsense variant (p.Trp411*), a likely pathogenic MSH6 frameshift variant, and a breast cancer PRS in the 99th percentile." (PMID 41919251, 2026). "Another notable rG4-altering variant was detected in the DNA mismatch repair gene MSH6, one of the breast cancer-implicated genes we examined." (PMID 41266338, 2025). "An unaffected patient carrying a BRCA1 and MSH6 variants had a family history of breast cancer (case #5)." (PMID 40943312, 2025). "Growing evidence suggests that MSH6 expression is significantly associated with tumor drug resistance and poor clinical outcomes, especially in MB, glioblastoma, bladder cancer, and breast cancer." (PMID 36452490, 2022). "MSH6 is associated with an increased risk for breast cancer and should be considered in individuals with a family history of breast cancer." (PMID 32746792, 2020). "In family B, the VUS in MSH6 p.Ser144Ile segregated with the two analyzed cases of breast cancer, one of them being bilateral, a hallmark of hereditary cancer." (PMID 32522261, 2020). "When evaluating by gene, only two of the four MMR genes were found to have a statistically significant increased association with breast cancer: MSH6 (SIR = 2.11; 95% CI, 1.56–2.86) and PMS2 (SIR = 2.92; 95% CI, 2.17–3.92)." (PMID 29345684, 2018). "In conclusion, our data demonstrate that PVs in MSH6 or PMS2 are associated with a modest but statistically significant increased risk for breast cancer." (PMID 29345684, 2018). "By testing a sequential series of breast cancer patients for 25 cancer predisposition genes, Tung and colleagues identified carriers of mutations in the MSH6 and PMS2 genes." (PMID 28637432, 2017). "We hypothesize that MM-65 mother’s breast cancer could be attributable to MSH6, since this gene has been associated with breast cancer predisposition, but this cannot be tested." (PMID 39516274, 2024). "In another multi-ethnic (European, African, Latin American/Caribbean, Asian) study including 35,000 women diagnosed with breast cancers, the prevalence of germline MSH6 pathogenic/likely pathogenic mutations is 2.2% in all breast cancers and 1.7% in the TNBC subgroup." (PMID 30630526, 2019). "In terms of extra-colon cancer risk, germline mutations in MSH6 and PMS2 have been associated with increased risks of both breast cancer and ovarian cancer, with a doubling of the likelihood of developing breast cancer by the age of 60 years." (PMID 38473212, 2024).
breast carcinoma (continued). "Germline mutations in MSH6 and PMS2 genes occur more frequently in Lynch syndrome-related breast cancer, and their polymorphisms are related to breast cancer occurrence and progression." (PMID 39334297, 2024). "Regarding clinical impact, the risk of developing basal or Her2 breast cancer was increased 15.7 times or 37.5 times for BRCA1 and MSH6 pathogenic variants respectively." (PMID 35451682, 2022). "More recently, the largest WES study for overall breast cancer reported increased breast cancer risk associated with ATM, CHEK2, PALB2, and MSH6." (PMID 35884425, 2022). "Compared to the general population, we found a statistically significantly increased risk of female breast cancer (SIR = 4.4, 95%CI 1.2–11.2) only in MSH6 carriers." (PMID 32448342, 2020). "Our data demonstrate that two LS genes, MSH6 and PMS2, are associated with an increased risk for breast cancer and should be considered when ordering genetic testing for individuals who have a personal and/or family history of breast cancer." (PMID 29345684, 2018). "MSH6 methylation was also quite common in the normal male breast, although at a lower frequency than our group of male breast cancer cases." (PMID 22765268, 2012). "As such, patients with MMR PVs, with the possible exception of MSH6, should not be advised that they are at increased risk of breast cancer." (PMID 34439310, 2021). "Many recent large-scale studies have published regarding this, including recent evidence that variants in the MMR genes MSH6 and PMS2 may be associated with an increased risk of breast cancer." (PMID 34439310, 2021).
breast carcinoma (continued). "Consequently, based on the survival data of the Kaplan-Meier plotter with Affymetrix 202911_at and 211449_at microarrays, we observed that the high expression of MSH6 was associated with poor prognosis of OS, RFS, PFS and DMFS prognosis in breast cancer cases." (PMID 34941572, 2021). "There are some MSH6 and PMS2 germline pathogenic variants implicated in breast cancer." (PMID 31307558, 2019). "Germline mutations in MSH6 are reported to be associated to breast cancer, but no extensive study on evaluation of MSH6 somatic mutations in breast tumor samples is reported." (PMID 30283497, 2018). "This study suggests that women with PVs in MSH6 or PMS2 may benefit from increased breast cancer screening." (PMID 29345684, 2018). "Here we show that PVs in MSH6 or PMS2 are associated with breast cancer and that these MMR genes should be considered when ordering a multigene panel for women with a personal or family history of breast cancer." (PMID 29345684, 2018). "Previously, the identification of a PV in MSH6 or PMS2 in a woman with breast cancer may have been considered an incidental finding." (PMID 29345684, 2018). "LoF variants in MSH6 showed evidence of a negative association with breast cancer risk." (PMID 35884425, 2022). "The MSH6 gene is also involved in genomic stability, and it has been suggested that G39E may be associated with breast cancer, but no conclusion has been reached yet." (PMID 34984555, 2022). "The nuclear DL model was validated for MSH6 in the colon, MSH6 and PMS2 in the endometrium, Ki-67 and CyclinB1 in prostate, and oestrogen and progesterone receptors in the breast cancer cohorts." (PMID 39040241, 2024). "There was one instance of a duplication in MSH6 in a colon cancer patient, and three patients with duplications of BRCA2 c.5557 within the same family, two of which reported breast cancer." (PMID 37306523, 2023). "S227 locus of MSH6 demonstrates higher phosphorylation level in primary tumor tissues of colon cancer, LUAD, breast cancer, clear cell RCC and UCEC compared with those normal tissues (all P <0.05)." (PMID 34941572, 2021). "Mechanistic studies probing the role of MSH6 and other MMR genes in breast cancer, and more particularly in the triple-negative subtype are awaited." (PMID 30630526, 2019).
breast carcinoma (continued). "The most frequently hypermethylated genes (MSH6, CDH13, PAX5, PAX6 and WT1) were similar for male and female breast cancer." (PMID 22765268, 2012). "Methylation is involved in the development of female breast cancer, with frequent methylation of PAX6, BRCA2, PAX5, WT1, CDH13 and MSH6 in ductal carcinoma in situ and invasive ductal cancer." (PMID 22765268, 2012). "On the other hand, the high frequency of methylation in MSH6, PAX5, PAX6 and CDH13 was shared between male and female breast cancer." (PMID 22765268, 2012). "In addition, we also detected a relationship between the high expression level of MSH6 and the poor OS (P=0.00052), PFS (P=0.007), RFS (P=6.5e-14) and DMFS (Distant metastasis-free survival) (P=0.00022) prognosis of breast cancer patients." (PMID 34941572, 2021). "It has been observed that mutation in MSH6 and PMS2 increases the risk of breast cancer by 30% and 35%, respectively, irrespective of other personal cancer history." (PMID 33182707, 2020). "Interestingly, genes with frequent methylation in male breast cancer (MSH6, CDH13, PAX5, PAX6 and WT1) were also very commonly methylated in female breast cancer." (PMID 22765268, 2012). "While some studies report an increased risk of breast cancer in PMS2 and MSH6 carriers, this could not be validated in other cohorts." (PMID 39684258, 2024). "Our larger study supports this finding and found significant differences in the prevalence of some breast cancer genes (BRCA1, MSH6, and MUTYH) between the two ethnic groups, suggesting that germline genetics may impact ethnic differences in breast cancer tumor characteristics and survival." (PMID 34857041, 2021). "We carried out a hospital-based case-control study in a Caucasian Portuguese population (287 cases and 547 controls) to estimate the susceptibility to non-familial breast cancer associated with some polymorphisms in mismatch repair genes (MSH3, MSH4, MSH6, MLH1, MLH3, PMS1 and MUTYH)." (PMID 19781088, 2009). "It is not until recently that the link between MSH6, PMS2, and breast cancers started to be comprehensively characterized." (PMID 30630526, 2019).
hereditary nonpolyposis colorectal cancer (70 papers, 2002 to 2026). "Mutations in human MSH6 are present in 12% of patients with hereditary non-polyposis colorectal cancer." (PMID 21437237, 2011). "Germline mutations in the MSH6 gene account for approximately 15-30% of cases of hereditary nonpolyposis colorectal cancer (HNPCC), whereas MSH6 germline mutations are seemed to be more common in EC than in CRC in some existing studies." (PMID 40469174, 2025).